AKT1 (AKT serine/threonine kinase 1)
Diseases named in the same sentence as AKT1 in open-access papers (continued):
Sharing a sentence is not in itself a finding about the gene and the disease.
spinal cord injury (7 papers, 2020 to 2026). Penetrating and non-penetrating injuries to the spinal cord resulting from traumatic external forces (e.g., WOUNDS, GUNSHOT; WHIPLASH INJURIES; etc.). "At the same time, the expression of AKT1 gene decreased, the results suggested that the increase of IL-1β affected the functional recovery of spinal cord contusion." (PMID 39262872, 2022). "In conclusion, IL-1β may affect neuronal apoptosis and regeneration through the regulation of mTOR, FOXO, and GSK3 expression via the PTEN/AKT1 signaling pathway, thereby affecting neuronal survival and functional recovery after spinal cord contusion." (PMID 39262872, 2022). "Moreover, after lentiviral interference with IL-1β, the expression of AKT1 increased and PI3K expression remained unchanged, and motor function was significantly restored in rats with spinal cord contusion." (PMID 39262872, 2022). "The experimental results showed that interfering with IL-1β can upregulate the expression of AKT1, thereby affecting the functional recovery of spinal cord contusion, but PI3K is not affected by IL-1β." (PMID 39262872, 2022).
acute lung injury (6 papers, 2015 to 2025). A condition of lung damage that is characterized by bilateral pulmonary infiltrates (pulmonary edema) rich in neutrophils, and in the absence of clinical heart failure. "In the subsequent experimental verification, further experiments are needed to validate the key role of AKT1 in regulating oxidative stress in the treatment of acute lung injury through L-Clausenamide." (PMID 40723395, 2025).
acute pancreatitis (6 papers, 2020 to 2025). An acute inflammatory process that leads to necrosis of the pancreatic parenchyma.
allergic asthma (6 papers, 2021 to 2025). A asthma with a basis in a pathological type I hypersensitivity reaction. "When considering the cumulative score, AKT1 appears to be the most probable promoter of allergic asthma, affecting 84.55% of the allergic asthma effectors." (PMID 33936056, 2021). "Screening results for phytocompounds of Z. rosea bulbs by GC-MS analysis were represented, which played a decisive role in the development of allergic asthma by affecting IL6, AKT1 and, Src genes." (PMID 39598467, 2024). "When looking at the cumulative score, the same combination of proteins (AKT1, STAT1, MAPK13, and TLR4) triggered 89.27% of the non-allergic asthma effector proteins and inclusion of the rest of proteins of interest would not substantially increase this percentage." (PMID 33936056, 2021).
allergic disease (6 papers, 2019 to 2025). An immune response that occurs following re-exposure to an innocuous antigen, and that requires the presence of existing antibodies against that antigen. "Therefore, the most promising protein combination as allergy triggers would be formed by AKT1, MAPK13, and STAT1 proteins." (PMID 33936056, 2021).
coronary heart disease (6 papers, 2013 to 2026). "Fructus Choerospondiatis (FC) components were found to regulate the PPAR signaling pathway, indicating a potential relationship between PPARG and AKT1 in the treatment of coronary heart disease." (PMID 38505269, 2024).
fallopian tube cancer (6 papers, 2020 to 2025). A primary or metastatic malignant neoplasm that affects the fallopian tube. "A report at the 2016 ASCO meeting showed a cohort of 379 patients with ovarian or fallopian tube carcinoma have been evaluated for 10 genes AKT1, AKT2, AKT3, mTOR, PIK3CA, PIK3C2B, PIK3R1, PTEN, TSC1, TSC2 in the PI3K/AKT/mTOR pathway." (PMID 38167649, 2024).
gout (6 papers, 2021 to 2026). A condition characterized by painful swelling of the joints, which is caused by deposition of urate crystals. "Based on each target’s degree value, AKT1 was regarded as the hub target of M. alba L. leaves against gout." (PMID 34502281, 2021). "Based on MDT, a hub bioactive of M. alba L. leaves against gout is γ-Tocopherol which had the strongest affinity on AKT1 (considered as a hub target against gout)." (PMID 34502281, 2021). "Among 26 compounds in M. alba L. leaves, γ-Tocopherol with the strongest affinity on AKT1 was the uppermost bioactive against gout." (PMID 34502281, 2021). "Therefore, the key mechanism of M. alba L. leaves against gout might be to suppress the inflammasomes in synovial fluids by inhibiting AKT1 by γ-Tocopherol, PRKCA by 4-Dehydroxy-N-(4,5-methylenedioxy-2-nitrobenzylidene) tyramine, and PLA2G2A by Lanosterol acetate on the RAS signaling pathway." (PMID 34502281, 2021). "AKT1 has the highest degree score in PPI and the strongest binding ability to key compounds, and is considered to be the pivotal target of Miaoyao Tongfengting decoction in the treatment of gout." (PMID 36595750, 2022). "The AKT1 of M. alba L. leaves against gout was directly connected to 14 out of 17 signaling pathways by the RAS signaling pathway, suggesting that the RAS signaling pathway might be a hub signaling pathway M. alba L. leaves against gout." (PMID 34502281, 2021).
gynecological cancer (6 papers, 2017 to 2025). "The mPFS for the ER-positive breast cancer, gynecologic cancer, and other solid tumor cohorts with AKT1-E17K-m (N=20, 15 and 17) were 5.5 months (95% CI, 2.9-6.9), 6.6 months (95% CI, 1.5-8.3), and 4.2 months (95% CI, 2.1-12.8), respectively." (PMID 40746599, 2025). "Comparison of AKT1 mutation detection data generated by castPCRTM, MALDI-TOF MS and BEAMing in 4 AKT1 E17K gynecological cancer samples." (PMID 28472036, 2017).
mammary adenocarcinoma (6 papers, 2016 to 2023). "However, recent investigations have now elegantly revealed the specific effects mediated by AKT1 and AKT2 isoforms in both the ErbB2-driven and the polyoma middle T (PyMT)-driven mammary adenocarcinoma transgenic mouse models." (PMID 29506489, 2018).
metastasis (6 papers, 2016 to 2026). The spread or migration of cancer cells from one part of the body (where they first appeared) to another. "Patient FNA-0330, who has three mutations (BRAF V600E/NRAS Q61R/AKT1), was confirmed as follicular thyroid carcinoma (FTC) with lymph node metastasis." (PMID 40586006, 2025).
pheochromocytoma (6 papers, 2016 to 2025). "Notably, associations with AKT1 and HSPA4 are not impaired in pheochromocytoma." (PMID 30943211, 2019).
urinary bladder urothelial carcinoma (6 papers, 2015 to 2025). "Mutations in FGFR3 and PIK3CA, singly or combined with RAS and AKT1, are associated with AKT but not with MAPK pathway activation in urothelial bladder cancer." (PMID 34229750, 2021).
autoimmune hepatitis (5 papers, 2022 to 2026). Hepatitis caused by autoantibodies. "As a consequence, 82 collective targets of celastrol and AIH were identified, among which PIK3R1, SRC, MAPK1, AKT1, and HRAS exhibited a closer association with autoimmune hepatitis." (PMID 35359864, 2022). "Thus, the key target genes for autoimmune hepatitis treatment mainly included AKT1, IL6, VEGFA, CASP3, JUN, MYC, etc.." (PMID 36558908, 2022).
bone tumor (5 papers, 2013 to 2023). "AKT1 (RAC-alpha serine/threonine-protein kinase) interacts with the NF-κB activation receptor, which is a critical signaling pathway in bone tumors and osteogenesis." (PMID 37311820, 2023). "CXCR4 expression is also enhanced in bone tumors, suggesting that CXCL12/CXCR4 signaling contributing to bone tumor growth in Akt1 transfected DU145 cells." (PMID 23902739, 2013). "Akt1 activation, as measured by Serine 473 phosphorylation, is higher in DU145-HA-Akt1 cells and is localized to the bone tumor interface, suggesting that transfected Akt1 is activated by bone remodeling-released and/or stromal-expressed factors." (PMID 23902739, 2013). "Herein, we utilized DU145-HA-Akt1 overexpressing cells to specifically determine the contribution of Akt1 without perturbing the lipid/protein phosphatase functions of PTEN in CXCR4 expression and downstream signaling in bone tumor growth." (PMID 23902739, 2013).
cyst (5 papers, 2012 to 2025). A sac-like closed membranous structure that may be empty or contain fluid or amorphous material. "So we concluded that DEHP exposure increased ROS and oxidative stress responsive miRNAs, then influenced the key genes in the PI3K/AKT1/mTOR signaling pathway and induced cell apoptosis in the newborn mouse ovaries, thereby influencing cyst breakdown and primordial follicle assembly." (PMID 31920986, 2019).
dementia (5 papers, 2021 to 2024). Loss of intellectual abilities interfering with an individual's social and occupational functions. "AKT1 can induce tumour formation through the upregulation of RNA binding protein EIF4G137, coronavirus exit from endosomes via valosin-containing protein VCP38 and MAPT-associated tau protein formation in dementia-like cognitive impairment." (PMID 36229517, 2022). "The serine-threonine protein kinase B (AKT1/2) and GSK3-β are involved in the brain insulin/insulin-like growth-factor-1 (IGF-1) signaling whose dysregulation correlates with the severity of dementia symptoms in sAD." (PMID 34830036, 2021).
insulinoma (5 papers, 2013 to 2022). "The initial increase in AKT1 expression that decreased with differentiation is consistent with β cell maturation, and the return to basal levels inconsistent with insulinoma." (PMID 35769100, 2022). "Surprisingly, we found that Akt1 controls β-cell size in an rpS6 phosphorylation-independent fashion, yet the development of insulinomas in Akttg mice is abolished if their β-cells lack rpS6 phosphorylation." (PMID 26919188, 2016). "Conceivably, the expression of constitutively active Akt1 could induce insulinoma via activation of the mTORC1 pathway and thereby its downstream effectors, S6K1 and rpS6 phosphorylation in β-cell (and the present report)." (PMID 26919188, 2016). "Rat primary β-cells and mouse insulinomas showed an adhesion remodeling during GSIS resulting from autocrine insulin/IGF2 and AKT1 signaling." (PMID 32934005, 2020).
intrahepatic cholangiocarcinoma (5 papers, 2022 to 2023). A carcinoma that arises from the intrahepatic bile duct epithelium in any site of the intrahepatic biliary tree. "Favorable prognosis of intrahepatic cholangiocarcinoma may be related to a dysregulated p-AKT1 expression." (PMID 36817485, 2023).
lipodystrophy (5 papers, 2019 to 2024). A congenital or acquired disorder characterized by abnormal loss or redistribution of the adipose tissue in the body. "In addition, Akt1/Akt2-DKO mice have dyslipogenesis, and AKT deficiency in adipocytes can lead to severe lipodystrophy." (PMID 33633792, 2021). "However, knocking out all adipocyte AKT activity by simultaneously deleting AKT1 and AKT2 in adipocytes, elicits an even more severe lipodystrophy phenotype, showing that AKT also regulates mTOR-independent adipocyte activities and that mTORC1-AKT interplay contributes to adipose tissue maintenance." (PMID 30781376, 2019).
lung diseases (5 papers, 2019 to 2024). "Some Stemona alkaloids are capable of preventing the progression of serious lung diseases by regulating the levels of AKT1 and PI3K through direct interaction with these proteins." (PMID 34205626, 2021).
lupus nephritis (5 papers, 2019 to 2026). Glomerulonephritis in the context of systemic lupus erythematosus. "In summary, our study unveils a critical pathogenic mechanism in lupus nephritis by establishing AKT1-mediated podocyte PANoptosis as a key driver of renal injury." (PMID 41573714, 2025).
macrodactyly (5 papers, 2012 to 2023). "In this study, we utilize an NGS-based strategy to identifiy mosaic PIK3CA and AKT1 variants in a cohort of 24 isolated macrodactyly patients." (PMID 33054853, 2020). "This study reports the largest series of patients so far with PIK3CA /AKT1-associated macrodactyly, which includes 24 patients with isolated macrodactyly, all of whom carry mosaic PIK3CA or AKT1 variants." (PMID 33054853, 2020). "In this study, 24 patients with macrodactyly underwent a targeted NGS-based sequencing and were identified to harbor mosaicism of either a pathogenic PIK3CA or AKT1 variant." (PMID 33054853, 2020). "No pathogenic or likely-pathogenic variant was detected in other genes currently known to be associated with macrodactyly, implicating somatic mosaicism of PIK3CA or AKT1 mutations as a predominant cause of isolated macrodactyly." (PMID 33054853, 2020). "However, patients with PIK3CA- or AKT1-driven macrodactyly or enlarged skeletal bones can present with either static or progressive overgrowth." (PMID 36621776, 2023).
muscle atrophy (5 papers, 2021 to 2026). The loss of muscle tissue due to inactivity or disease. "Our molecular docking results showed that Aloin A had good binding interactions with HSP90AA1, AKT1, CTNNB1, BCL2L1, RELA, TNF, AKT3, the ranging from −7.9 to −8.9 kcal/mol, suggesting that Aloin A stably combined with these proteins for attenuating cancer related muscle atrophy." (PMID 38180061, 2023).
Osteopenia (5 papers, 2007 to 2024). Osteopenia is a term to define bone density that is not normal but also not as low as osteoporosis. "This study initially showed that the disruption of Akt1, a major Akt in osteoblasts and osteoclasts, in mice led to low-turnover osteopenia through dysfunctions of both cells." (PMID 17957242, 2007). "The present study initially analyzed the bones of mice lacking Akt1 and found that the deficiency caused osteopenia with a low turnover state." (PMID 17957242, 2007). "Mice lacking Akt1 have been found to show insufficient bone mass gain at an early age and osteopenia at adulthood, reflecting the potential osteoblast-specific effects of the PI3K/Akt signaling pathway." (PMID 36629528, 2023).
penile cancer (5 papers, 2011 to 2025). A primary or metastatic malignant neoplasm that affects the penis. "Cytoplasmic Akt1 was positive in 37% (54/147) of penile cancers and it strongly correlated with tumour grade (p = 0.0001)." (PMID 21407808, 2011). "Copy number alterations of AKT1 were described in penile carcinomas." (PMID 36564761, 2022). "pAkt and Akt1 immunoexpression did not correlate with HPV in our penile cancer series." (PMID 21407808, 2011).
RASopathies (5 papers, 2019 to 2023). "The protein corresponding to the node with most associations with other genes within the RASopathy interactome is AKT1 with 199 associations reported." (PMID 34229750, 2021). "Immunoblotting results show that dysregulation on several phosphoproteins account for more than one RASopathy, including ERK1/2 (Thr202/185 and Tyr204/187), AKT1 (Thr308 and Ser473), MEK1 (Thr292) and RAF1 (Ser259), which are the most co-occurring studied proteins along the syndromes." (PMID 34229750, 2021).
skull base meningioma (5 papers, 2020 to 2025). A meningioma that arises from the skull base. "Among skull base meningiomas, AKT1 mutations were found at a higher frequency of 30% and was shown to be associated with shorter time to recurrence." (PMID 36686824, 2022). "Concerning the three NF2-wild type IVMs, none had mutations in AKT1, PIK3CA or SMO genes, which are typically altered in skull base meningiomas." (PMID 35049691, 2022). "In cases of NF2-mutant skull base meningiomas refractory to surgery and radiation, currently, there is no effective chemotherapy; however, PIK3CA, SMO and AKT1 represent promising future therapeutic targets." (PMID 40075786, 2025).
tongue squamous cell carcinoma (5 papers, 2020 to 2025). A squamous cell carcinoma that arises from the tongue. "But, recent studies found that miR-138 binding to AKT1 regulates the expression of AKT1 in tongue squamous cell carcinoma." (PMID 35430805, 2022).
acute liver failure (4 papers, 2019 to 2023). Rapid deterioration of liver function causing encephalopathy and coagulopathy. "Since ConA is known to cause acute liver failure via an immunologic activated cytokine response syndrome with TNF-α and INF-γ as the pivotal mediators, these data implied that AKT1-MSCs had a superior protective effect on immune-mediated hepatitis." (PMID 31889917, 2019).
allergic rhinitis (4 papers, 2022 to 2023). Inflammation of the nasal mucous membranes caused by an IgE-mediated response to external allergens.
ameloblastoma (4 papers, 2020 to 2025). The most common odontogenic tumor, arising from the epithelial component of the embryonic tooth and usually affecting the molar-ramus region of the mandible or maxilla. "With these bioinformatic analyses it is possible that pathogenic ameloblastoma development involve these genes in intracellular regulation (AKT1, ACTC1, ADAM10, and APOA2) or for tumor microenvironment regulation (CRP, BCHE, APP, AGT)." (PMID 36553196, 2022). "In the present case we report a AKT1 c.49G > A p.(Glu17Lys) exon 4 variant, a hotspot mutation which is commonly associated with various cancers, including breast, colorectal and lung, but has also been recently identified in an ameloblastoma with a BRAF mutated background." (PMID 41144131, 2025). "However, only AKT1 has reports to indicate their association with the regulation of TNFalpha-AKT-MAPK pathway signaling, which promotes cell survival and proliferation in ameloblastoma." (PMID 36553196, 2022).
Bladder tumors (4 papers, 2014 to 2024). "The IHC score of AKT1 remarkably increased at the protein level in bladder tumours compared with adjacent tissue." (PMID 35522942, 2022).
chronic heart failure (4 papers, 2013 to 2024). "There is additional evidence that coronary delivery of constitutively active form of Akt1 gene protects the heart against doxorubicin-induced chronic heart failure by improving cardiac performance." (PMID 24147064, 2013).
ductal carcinoma in situ (4 papers, 2010 to 2022). "The overexpression of AKT1 in MCF10A cells grown in 3D Matrigel and injected into the mouse mammary duct, resemble ductal carcinoma in situ-like lesions." (PMID 28287129, 2017).
germ cell tumor (4 papers, 2018 to 2023). A benign or malignant, gonadal or extragonadal neoplasm that originates from germ cells. "PIK3CA and AKT1 mutations have been identified in cisplatin-resistant germ cell tumors, and phospho-AKT levels are significantly higher in cisplatin-resistant TGCTs compared with cisplatin-sensitive ones." (PMID 33212946, 2020).
hypothyroidism (4 papers, 2021 to 2026). Abnormally low levels of thyroid hormone. "In contrast, α-lipoic acid treatment attenuated oxidative stress, improved folliculogenesis, reduced histopathological damage, and reversed PTU-induced hypothyroidism alterations in PI3K/AKT1 signaling and GRP78 expression (p < 0.05)." (PMID 41790217, 2026). "In our research, the deterioration in the LTP response was attributed to an increase in Akt1-mRNA level and a decrease in Gsk3ß-mRNA level in rats with hypothyroidism." (PMID 39128046, 2024).
leiomyoma (4 papers, 2021 to 2023). A well-circumscribed benign smooth muscle neoplasm characterized by the presence of spindle cells with cigar-shaped nuclei, interlacing fascicles, and a whorled pattern. "Protein expression levels of phosphorylated ERK1/2/total ERK1/2, phosphorylated STAT3/total STAT3, and phosphorylated AKT1/2/3/total AKT1/2/3 were quantified using immunoblotting in immortalized and primary leiomyoma and myometrial cells cocultured with human adipocytes and treated with leptin." (PMID 36771423, 2023).